GPR35 (G protein-coupled receptor 35)
Diseases named in the same sentence as GPR35 in open-access papers (continued):
Sharing a sentence is not in itself a finding about the gene and the disease.
atherosclerosis (4 papers, 2015 to 2023). A disease characterized by the build-up of fatty material and calcium deposition in the arterial wall resulting in partial or complete occlusion of the arterial lumen. "This study identified an association between a non-synonymous GPR35 SNP and coronary artery calcification, a risk factor in atherosclerosis and coronary artery disease." (PMID 25805994, 2015). "Given that overactivation of the NLRP3 inflammasome leads to inflammatory diseases such as Alzheimer’s disease, gout, and atherosclerosis, KA or other agonists of GPR35 might have potential as new therapeutics for NLRP3-triggered diseases." (PMID 36311752, 2022). "Whether GPR35 plays a role in vascular inflammation and the development of atherosclerosis is unknown." (PMID 34201526, 2021). "A GWAS analysis study has identified an association between a single nucleotide polymorphism (rs3749172) in GPR35 and a high degree of coronary artery calcification (CAC) measured by computed tomography, which is used as a surrogate marker of the total burden of atherosclerosis." (PMID 34201526, 2021). "Since LPA is associated with numerous pathological conditions including atherosclerosis, cancer, obesity, impaired glucose homeostasis, and pain, there is a need to clarify the relevance of this reported effect of LPA at GPR35." (PMID 25805994, 2015). "Our study indicates that GPR35 expression does not play a direct role in macrophage activation, vascular inflammation, and the development of atherosclerosis." (PMID 34201526, 2021). "In conclusion, we have demonstrated that the lack of GPR35 expression in blood cells does not influence vascular inflammation and atherosclerosis." (PMID 34201526, 2021). "Although GPR35 signaling has been proposed to trigger anti-inflammatory responses in the gut and adipose tissue, we show that the ablation of GPR35 signaling in bone marrow-derived cells did not influence vascular inflammation and atherosclerosis in hyperlipidemic mice." (PMID 34201526, 2021). "Whether GPR35 can influence vascular inflammation and atherosclerosis has however never been tested." (PMID 34201526, 2021).
breast carcinoma (4 papers, 2019 to 2022). "The CXCL17-CXCR8 (GPR35) signaling axis promotes the proliferation and migration of breast cancer cells in vitro and in vivo." (PMID 35535309, 2022). "For a lung metastasis model of breast cancer, researchers have found that breast cancer cells promote GPR35+MDSC colonization in the lung by secreting CXCL17 and G-CSF." (PMID 34689842, 2021). "GPR35 has been reported to be up-regulated in breast cancer tissue compared with normal adjacent tissue, but the overall significance of this remains uncertain." (PMID 30601679, 2019).
fatty liver disease (4 papers, 2021 to 2025). A reversible condition wherein large vacuoles of triglyceride fat accumulate in liver cells via the process of steatosis. "Notably, in HFD conditions, Gpr35 deficiency led to the upregulation of Cidea, which correlated with exacerbated hepatic steatosis in Gpr35 KO mice." (PMID 39873004, 2024). "Ultimately, this research holds the promise of offering valuable insights into the underlying mechanisms governing liver zonation and the molecular basis of GPR35 involving in regulating lipid metabolism and fatty liver disease." (PMID 39873004, 2024). "Our primary focus is on illuminating the role of GPR35 in influencing liver zonation and its implications for the development and progression of fatty liver disease." (PMID 39873004, 2024). "Here, we have integrated SM and ST approaches to investigate liver zonation and elucidate the mechanistic role of GPR35 in the regulation of fatty liver disease." (PMID 39873004, 2024). "Overexpression of GPR35 in hepatocytes prevented steatohepatitis in models subjected to high-fat/cholesterol/fructose diet, while GPR35 knockout models showed aggravated metabolic disorders and hepatic steatosis." (PMID 41415839, 2025). "The identification of specific genes regulated by GPR35 in the hepatic steatosis process carries substantial significance, as it offers valuable insights into the role of GPR35 and unveils potential targets for treating fatty liver." (PMID 39873004, 2024). "While previous studies have implicated GPR35 in the context of metabolic dysfunction-associated steatotic liver disease (MASLD) and MASH, its precise function in fatty liver disease and how it modulates metabolism in specific liver zones remain to be fully characterized." (PMID 39873004, 2024). "Furthermore, Gpr35 KO mice exhibited increased hepatic steatosis compared to WT mice." (PMID 39873004, 2024). "In hepatocytes from these humanized GPR35 mice,activation of this receptor was shown conclusively to prevent, andalso reverse, lipid accumulation induced by liver X-receptor stimulation.These studies highlight the potential to target GPR35 in the contextof fatty liver diseases." (PMID 34927014, 2021).
ischemia (4 papers, 2023 to 2025). A hypoperfusion of the BLOOD through an organ or tissue caused by a PATHOLOGIC CONSTRICTION or obstruction of its BLOOD VESSELS, or an absence of BLOOD CIRCULATION. "The activation of GPR35 triggered the dimerization of ATP synthase in a manner reliant on ATPIF1 and sensitive to pertussis toxin, thereby inhibiting the loss of ATP due to ischemia." (PMID 40736072, 2025). "Somehow similar, G protein–coupled receptor 35 (GPR35) appeared to interact indirectly with IF1 and was activated in an IF1-depedent manner, which then induced ATP synthase dimerization, which prevented ATP loss upon ischemia." (PMID 37469400, 2023).
myocardial infarction (4 papers, 2015 to 2026). Gross necrosis of the myocardium, as a result of interruption of the blood supply to the area, as in coronary thrombosis. "Kynurenic acid (KynA), a tryptophan metabolite that regulates immune homeostasis via G protein-coupled receptor 35 (GPR35), has an undefined role in post-myocardial infarction (MI) immune responses." (PMID 41897447, 2026). "Inhibition of GPR35 preserves mitochondrial function after myocardial infarction by targeting Calpain 1/2." (PMID 34943862, 2021).
cognitive deficits (3 papers, 2025 to 2026). "GPR35 deficiency exacerbates seizure susceptibility and cognitive deficits." (PMID 41604576, 2026). "We further demonstrate that GPR35 activation mitigates seizures, suppresses hippocampal neuroinflammation, and alleviates cognitive deficits." (PMID 41604576, 2026). "Changes in the expression of Ahr, GPR35, and KP enzymes may modulate the neuronal response to damaging agents, influencing the progression and severity of cognitive impairment." (PMID 41155178, 2025). "No significant changes in the expression of katI, katII, kmo and ahr and gpr35 genes were observed, suggesting a lack of activation of this pathway in transient cognitive deficits induced by muscarinic receptor blockade." (PMID 41155178, 2025). "Furthermore, as an endogenous agonist of Gpr35, KYNA has been systematically evaluated in cognitive disorders through a comprehensive review and meta-analysis." (PMID 40862055, 2025).
coronary artery disease (3 papers, 2012 to 2018). "The first study to suggest a cardiovascular role for GPR35 was a GWAS of hypertensive individuals, which aimed to identify novel predictors of coronary artery disease." (PMID 25805994, 2015).
intestinal tumour (3 papers, 2022 to 2025). "We have shown that GPR35 promotes intestinal tumour growth and the turn-over of the intestinal epithelium by promoting Na+/K+-ATPase-dependent Src kinase activation." (PMID 40121360, 2025). "GPR35 increased intestinal tumour formation by promoting tumour cell proliferation and tumour angiogenesis." (PMID 40121360, 2025). "Meanwhile, we found that GPR35 not only has high expression in intestinal tumors (such as COAD and READ), but also in GC." (PMID 36333291, 2022). "GPR35 critically controls the size of intestinal tumours in murine spontaneous (APCmin) and CAC (AOM/DSS) models." (PMID 33758004, 2022).
metabolic dysfunction-associated steatotic liver disease (3 papers, 2024 to 2025). Metabolic dysfunction-associated steatotic liver disease (MASLD, formerly known as nonalcoholic fatty liver disease or NAFLD) is a type of liver disease that is not caused by alcohol. "Spatial multi-omics analysis has shown that GPR35 knockout mice fed a high-fat diet exhibit excessive weight gain, exacerbated nonalcoholic fatty liver disease, and increased hepatic triglyceride accumulation, all established risk factors for HCC development." (PMID 41459506, 2025).
non-small cell lung carcinoma (3 papers, 2020 to 2023). A group of at least three distinct histological types of lung cancer, including non-small cell squamous cell carcinoma, adenocarcinoma, and large cell carcinoma. "A recent study demonstrated that in non-small-cell lung cancer, Akt inhibition resulted in suppression of GPR35 expression." (PMID 32523084, 2020). "In parallel, and in comparison to paired normal tissues, the expression of GPR35 was reduced in prostate, testicular and thyroid tumors; increased in stomach, pancreatic, colon and non-small-cell lung cancer, and unaltered in breast and ovarian cancer." (PMID 33113952, 2020). "Functionally, GPR35 signaling pathway via ERK kinase has been involved in several cellular processes such as proliferation, cell survival and even metastasis, and overexpression of GPR35 seems to confer drug resistance in non-small-cell lung cancer through β-arrestin-2/Akt signaling." (PMID 33113952, 2020).
osteoporosis (3 papers, 2022 to 2025). A condition of reduced bone mass, with decreased cortical thickness and a decrease in the number and size of the trabeculae of cancellous bone (but normal chemical composition), resulting in increased fracture incidence. "Gpr35-knockout mice have reduced bone mass, while GPR35 agonism rescues bone loss in rodent osteoporosis models, indicating that GPR35 has an important role in bone." (PMID 40978132, 2025). "Previous studies have indicated that GPR35 is downregulated in individuals with osteoporosis and in mouse models of the disease and that activation of GPR35 improves bone density in osteoporotic mice." (PMID 40215127, 2025). "Expression of the GPR35 gene and protein is downregulated in osteoporosis patients and in mouse models of the disease." (PMID 40978132, 2025). "Finally, we compared the ability of GPR35 agonists to suppress osteoclast activity to that of current osteoporosis drugs, denosumab and alendronic acid, and showed TRAP activity was similarly suppressed under all conditions." (PMID 40978132, 2025). "Although previous studies indicate that expression of the GPR35 gene is reduced in humans and mice with osteoporosis, stimulation of monocytes with GPR35 agonists significantly increased GPR35 expression in pre-osteoclasts and mature osteoclasts, indicating that the receptor is a viable target." (PMID 40978132, 2025). "GPR35 represents a promising novel target to reduce osteoclast activity that could be exploited for osteoporosis treatments." (PMID 40978132, 2025). "Finally, we compared the ability of the GPR35 agonists to reduce osteoclast activity to two currently available osteoporosis drugs, denosumab and alendronic acid (alendronate)." (PMID 40978132, 2025). "We have demonstrated that stimulation of GPR35 in primary human osteoclasts impairs osteoclast activity and may be a viable target in osteoporosis therapies." (PMID 40978132, 2025). "Previous studies have indicated that GPR35 expression is reduced in bone marrow mesenchymal stem cells of humans and mice with osteoporosis, which could limit the feasibility of targeting GPR35." (PMID 40978132, 2025). "Finally, we assessed how GPR35-induced reductions in osteoclast activity compare to two existing osteoclast-targeted osteoporosis drugs." (PMID 40978132, 2025). "Drugs that stimulate GPR35 could have anti-resorptive and anabolic effects on bone and represent a viable new target for osteoporosis treatments." (PMID 40978132, 2025). "Additional studies may also be required to establish whether GPR35 expression in osteoclasts is affected by age and to determine whether the agonist-induced increase in gene expression is retained in cells derived from individuals with osteoporosis." (PMID 40978132, 2025). "Therefore, GPR35 agonism could have both anti-resorptive and anabolic effects on bone and is a promising candidate for osteoporosis treatment." (PMID 40978132, 2025). "GPR35 agonists reduced TRAP activity in osteoclasts and co-cultures to similar levels to denosumab and alendronic acid, which are currently used to treat osteoporosis." (PMID 40978132, 2025). "Previous studies in mice showed that GPR35 activation improves bone density in osteoporosis by direct actions on osteoblasts, but neither of these studies assessed osteoclast effects." (PMID 40978132, 2025). "G protein-coupled receptor 35 is widely expressed in immune cells, cardiomyocytes, hepatocytes, the gastrointestinal tract, and dorsal root ganglia, and off-target effects on these cells must be considered if GPR35 is to be targeted in osteoporosis." (PMID 40978132, 2025).
pancreatic cancer (3 papers, 2023 to 2025). "The similar results were observed in High-GPR35 and Low-GPR35 groups in pancreatic cancer (p = 0.57)." (PMID 39990208, 2025). "The expression of GPR35 is significantly elevated in PDAC tumor tissues, and its expression level shows a positive correlation trend with tumor stage, grade, and resectability, suggesting it may represent a potential biomarker for pancreatic cancer." (PMID 41459506, 2025).
Parkinson disease (3 papers, 2013 to 2025). A progressive degenerative disorder of the central nervous system characterized by loss of dopamine producing neurons in the substantia nigra and the presence of Lewy bodies in the substantia nigra and locus coeruleus. "GPR35 is an orphan G protein-coupled receptor and is associated to inflammation, cardiovascular diseases, metabolic disorders, Parkinson’s disease and other neuronal disorders." (PMID 32272735, 2020). "GPR35 agonists, as catechol-O-methyl transferase inhibitors, are commonly used for the treatment of Parkinson’s disease." (PMID 32272735, 2020). "Second, the agonistic activity at the GPR35 is a commonly observed property of drugs used for treating Parkinson disease; these drugs include entacapone, tolcapone and nitecapone, L-DOPA, and benserazide (this study)." (PMID 24276120, 2013). "Although the mechanism behind is largely unknown, all these compounds are GPR35 agonists, suggesting a possible role of GPR35 in Parkinson’s disease and other neuronal disorders, which is currently under investigation." (PMID 24276120, 2013).
type 2 diabetes (3 papers, 2015 to 2025). "Prior to the IBD GWAS, the neighboring genes CAPN10 and GPR35 had both previously been linked with disease in a GWAS for type 2 diabetes mellitus." (PMID 25805994, 2015). "Abnormalities in the coding and intergenic regions of GPR35 have been reported to be associated with metabolic diseases such as type 2 diabetes, and activation of GPR35 has been shown to prevent lipid accumulation by increasing energy expenditure in adipose tissue." (PMID 41415839, 2025). "This study identified four non-synonymous SNPs in the coding region of GPR35, with only ‘UCSNP-38,’ which encodes a serine to arginine substitution at amino acid position 294, showing an association with type 2 diabetes." (PMID 25805994, 2015). "The study therefore concluded that the genetic variation in CAPN10, and not GPR35, was responsible for the disease susceptibility, and no further evidence for a role of GPR35 in type 2 diabetes has since been reported." (PMID 25805994, 2015). "Given its multifaceted roles in improving insulin sensitivity, glycemic control, lipid metabolism, body weight regulation, and inflammatory responses, GPR35 has emerged as a promising therapeutic target for metabolic disorders such as type 2 diabetes mellitus (T2DM), obesity, and NAFLD." (PMID 41459506, 2025).
Cerebral ischemia (2 papers, 2020 to 2022). Restriction of arterial blood supply to the brain associated with insufficient oxygenation to support the metabolic requirements of the tissue. "Activation of GPR35 can also protect against cerebral ischemia by recruiting monocyte-derived macrophages." (PMID 35087615, 2022). "Until now, the impact of GPR35 activation in cerebral ischemia is not known." (PMID 32523084, 2020).
Glucose intolerance (2 papers, 2025). Glucose intolerance (GI) can be defined as dysglycemia that comprises both prediabetes and diabetes. "Gpr35 knockout mice exhibit progressive weight gain and glucose intolerance, indicating that GPR35 deletion disrupts glycolysis-dependent energy metabolism and impairs overall metabolic health." (PMID 41459506, 2025). "Genetic deletion of G‐protein coupled receptor 35 (GPR35) in mice leads to excessive weight gain, glucose intolerance, and increased abundance of R. gnavus, indicating a relationship between downstream GPR35 signaling, metabolic syndrome, and microbiota composition." (PMID 39589934, 2025). "Notably, Gpr35−/− mice exhibit weight gain and glucose intolerance, further underscoring the receptor’s central role in lipid and glucose metabolism." (PMID 41459506, 2025).
migraine (2 papers, 2015 to 2024). "Furthermore, GPR35 activation has been shown to regulate the secretion of pro-inflammatory cytokines, potentially modulating the inflammatory environment linked to migraine." (PMID 39107712, 2024). "Additionally, GPR35 modulates pain perception, influencing nociceptor function and pain signaling, presenting it as a potential target for pain management in migraine patients." (PMID 39107712, 2024). "The study of kynurenine metabolites in models of migraine has been focused on KYNA, which displays pleiotropic actions in the CNS by inhibiting NMDA receptors and α7-nicotinic acetylcholine receptors, and activating the GPR35 G-protein coupled receptor." (PMID 27130315, 2015).
schizophrenia (2 papers, 2019 to 2021). A major psychotic disorder characterized by abnormalities in the perception or expression of reality. "The overlapping structural, pharmacological, and anatomical properties between GPR35 and CBRs are also promising candidates for regulating the common aspects of inflammation associated with schizophrenia." (PMID 31619006, 2019). "At last, KYNA has been shown to possess agonist activity at an orphan G-protein-coupled receptor (GPR35), which predominantly detected in immune cells and the gastrointestinal tract, but no data is available about a link between the GPR35 function and the pathophysiology of schizophrenia." (PMID 34576179, 2021).